IL6 (interleukin 6)
Diseases named in the same sentence as IL6 in open-access papers (continued):
Sharing a sentence is not in itself a finding about the gene and the disease.
tumor (continued). "We examined whether HSV remains a significant predictor for IL-6 plasma concentration if other patient- and tumor-related variables potentially influencing IL-6 levels were included into a multiple regression analysis." (PMID 34773163, 2022). "Furthermore, we showed that the increase in tumor-infiltrating myeloid CD45+ cells and the amount of circulating cytokine IL-6 and chemokine KC (also known as CXCL1) is associated with a higher tumor size in different strains." (PMID 36037073, 2022). "The data revealed that elevated levels of IFNα (∼25.62 pg/ml), IFNβ (∼38.71 pg/ml), TNFα (∼72.64 pg/ml), IL‐6 (∼139.26 pg/ml), IL‐12p40 (∼100.78 pg/ml), and IL‐10 (∼23.06 pg/ml) were detected in the tumours treated with 3p‐125b‐ASO‐loaded RBCEVs as compared to the controls." (PMID 35430766, 2022). "Moreover, other studies have reported that the supernatant from HPV-positive tumor cell lines, which contains the secreted IL-6 and prostaglandin E2, induces a suppressor phenotype in immune cells." (PMID 36010260, 2022). "IL-6 also upregulates the expression of fascin-1 (an actin filament bundling protein) that regulates cytoskeletal structures, resulting in the formation of protrusions related to cell motility for the migration and increased invasion potential of tumor cells." (PMID 35205842, 2022). "Additionally, we found a significant correlation between the IL-6 peak and tumor burden, which potentially explains why patients with a high tumor burden are more likely to develop sCRS." (PMID 35013456, 2022). "Interestingly, during the adoptive transfer of activated OT-I lymphocytes into tumor-bearing mice, the cytokine that was more highly induced was IL-6." (PMID 36443756, 2022). "Currently, chemotherapy exposure markedly increases the release of inflammatory cytokines such as IL-6 and IL-8 in the tumor microenvironment, promoting cancer cell survival and self-renewal signaling of cancer stem cells, which are crucial for drug resistance and relapse." (PMID 35326493, 2022). "We identify the existence of a molecular mechanism shielding the tumor from immune attack regulated by the IL-6/STAT3/SMG1 axis that prevents antitumor immune responses: a new immunoediting process to silence potent neoantigens by immune intrinsic pathways that affect the activity of NMD." (PMID 36443756, 2022). "Moreover, CD4(+) T cells in peritumor secrete large amount of IL-6 in clear cell renal carcinomas (ccRCC), which favors the alteration of tumor cell morphology as well as the acquisition of EMT and stemness phenotypes." (PMID 35251963, 2022). "Likewise, the cells of the tumor located in the primary site produce many factors, such as IL-1, IL-6, IL-11, PDGF, MIP-1α, TNF, M-CFS, RANKL, and PTHrP, directly stimulating osteoclasts to form osteoclastic-type lesions." (PMID 36230523, 2022). "Obvious expression of IL‐6 protein was observed in proximal sites of N‐inv tumor." (PMID 35578571, 2022). "Higher plasma IL-6 level often clinically indicates advanced and metastasis tumor." (PMID 35069767, 2022). "IL-6 signaling can be targeted in a variety of ways, including the use of anti-IL-6 (siltuximab) or IL-6R (tocilizumab) monoclonal antibodies, which have both been extensively studied in different experimental tumor models as well as in clinical trials." (PMID 36405719, 2022). "Thus, IL-9 controls tumour cell proliferation in colorectal neoplasias via IL-6 and impairs barrier function markedly." (PMID 35793807, 2022). "Importantly, comparing WT mice with IL-6 KO mice, both treated with the combination of gDE7 + IDO inhibitors, we observed a significantly decreased in tumor growth in IL-6 defective mice, especially when treated with D-1MT." (PMID 36405719, 2022). "It is worth noting that the response of these cell populations could be viewed as indicators of how clinically depleting tumor IL-6 with targeted agents such as tocilizumab could influence the efficacy of checkpoint immunotherapies." (PMID 36142210, 2022).
tumor (continued). "Tumor-associated macrophages make up a large majority of noncancerous cells in tumors and are major producers of IL-6." (PMID 35626018, 2022). "Notably, even though anti-IL6 treatment did not influence tumour volume, the percentage of Tregs and Gr-MDSCs decreased by a factor of two, and the CD8/Tregs ratio increased in anti-IL-6-treated tumours, compared to control tumours." (PMID 36077801, 2022). "Plasma IL-6 is a promising surrogate marker for tumor hypoxia dynamics in HNSCC patients and may facilitate hypoxia-directed personalized radiotherapy concepts." (PMID 34773163, 2022). "These anti-inflammatory effects targeting transcription factors STAT3 and NF-κB and cytokine IL-6 on macrophage might contribute to the anti-tumor immune microenvironment by blocking the polarization of macrophages into M2." (PMID 35890318, 2022). "A classic example is the nuclear factor kappa-light-chain-enhancer of activated B cells (NF-kB), a central transcription factor that is commonly activated in both tumor and immune cells to produce inflammatory cytokines, chemokines and growth factors, such as IL-1β, IL-6 and CCL2." (PMID 35757000, 2022). "Moreover, CXCL12 also affects the tumour microenvironment, and its combination with IL-6 can mediate the homing and proliferation of tumour cells." (PMID 36312898, 2022). "IL‐6‐mediated STAT3 activation is common in the tumor microenvironment." (PMID 37829248, 2022). "For instance, TGFβ could be identified as a potent inhibitor of IL-6-mediated tumor-supportive effects, whereas Th9 cell-released IL-9 is apparently able to increase I-L6 and IL-9 production by intratumoral Th9 cells in an auto-amplifying loop." (PMID 36428508, 2022). "Specifically, IL-6 is released by cells in the tumor microenvironment and increases the production and subsequent release of VEGF into the environment via the IL-6/STAT3/VEGFA pathway, promoting endothelial cell activation and the subsequent formation of tubular structures." (PMID 36555614, 2022). "JAK-STAT signaling is highly active in CSCs, and studies have reported that activation of STAT-3 by IL-6 has a profound effect on tumor initiation and progression, invasion and metastasis by protecting tumor cells from apoptosis, driving epithelial–mesenchymal plasticity, and enhancing angiogenesis." (PMID 36466926, 2022). "IL-1α, IL-6, and IL-8 can promote immune processes involving the killing of tumor-related cells and induce apoptosis, which has the effect of directly inhibiting and killing tumor cells." (PMID 35855902, 2022). "Moreover, in agreement with previous findings in other tumor types harboring oncogenic KRAS mutations, we also found that KRASG12D can promote IL6 expression in CCA cells." (PMID 35619118, 2022). "The observation of staining Patterns 1 and 3 in human IBC specimens raised the intriguing possibility that in certain IBC tumors, IL-6 may be supplied in trans from one tumor cell clone to a second clone expressing IL-6R." (PMID 35565421, 2022). "Notably, in BC tissue, Th17 cells are positively related to the IL-6, IL-1β, and IL-17 expression, and also negatively correlated with an increase in the number of metastatic lymph nodes and angiogenesis of tumor cells as well." (PMID 35248028, 2022). "In addition, proinflammatory cytokines stimulate lipolysis and fat oxidation in humans, and increased tumor-secreted IL-6 is characteristic in animal models of cancer cachexia, as well as in cachectic cancer patients." (PMID 36277179, 2022). "Numerous studies have demonstrated the negative effect of certain cytokines, especially IL-6, which has been associated with tumor progression." (PMID 35888601, 2022).
tumor (continued). "In cancers, the IL-6 cytokine family not only directly affects the proliferation, survival, invasion, and metastasis of tumor cells, but also participates in shaping the local tumor microenvironment (TME) by modulating inflammation, immunosuppression, and angiogenesis." (PMID 35265072, 2022). "Adipocytes and their precursor cells can influence tumor behavior via various hormones, growth factors, and cytokines known as adipokines including leptin, adiponectin, IL-6, hepatocyte growth factor, autotaxin, and TNF-alpha although their exact mechanism of action has not been established." (PMID 34532758, 2022). "IL-6, another abundant cytokine present both at tissue and systemic levels in PCa patients, limits NK cell anti-tumor activities, via STAT3 activation, by decreasing MICA/B and ULBPs NK cell-activating ligands, resulting in decrease NK cell killing capabilities." (PMID 36338516, 2022). "In addition, TNF-alpha, IL-17, and IL-6 have also been shown to induce tumor growth through NF-kappa B and STAT3 activation." (PMID 35563010, 2022). "Next, we measured the expression of IFN-γ, PD-L1, and IL-6 in the tumor." (PMID 35444660, 2022). "In clinical samples, serum IL6 relates both with tumor initiation and progression." (PMID 35911788, 2022). "Based on the first and third scenarios, we hypothesized that certain clones within a tumor lesion may provide IL-6 in trans to promote the growth of adjacent clones." (PMID 35565421, 2022). "Many recent reports have demonstrated a role for IL-6 as a driver of tumor drug resistance." (PMID 35356749, 2022). "IL-6 produced in ovarian clear cell carcinoma (OCCC) cells stimulates the common tumorigenic gene expression pattern by regulating the expression of SPINK1 to promote tumor peritoneal metastasis, anoikis resistance and proliferation." (PMID 35223512, 2022). "The highly expressed IL-6 can promote inflammation and tumor cell immunosuppression, and possibly aggravate tumor cell growth and metastasis by IL-6/Signal Transducer And Activator Of Transcription 3 (STAT3) mediated inhibition of DC and lead to the dysfunction of the immune system." (PMID 36004920, 2022). "In addition, both spleen tumor tissues and tumor growth were decreased in GRA15-polarized macrophages-injected tumor-bearing C57BL/6 mice, and IL-6 expression was also decreased in tumor tissue." (PMID 36341349, 2022). "The tumor sample stained positive for G-CSF and IL-6, thus indicating a CST." (PMID 36010260, 2022). "The pro-inflammatory cytokines (such as tumor necrosis factor-α, interleukin-6, and interleukin-1β) from visceral adipose tissue contribute to a chronic inflammatory state in the whole body, thus creating a general environment better suitable for tumor growth." (PMID 36245841, 2022). "It has been widely described how inflammatory cytokines, such as TNF-α, IL-1, and IL-6, can be produced by tumor cells, fact which may explain the link between cancer and inflammation." (PMID 35457471, 2022). "Finally, the levels of cytokines, such as IFN-γ and IL-6 in the serum were greatly increased in CR mice compared to those in naive mice after tumor rechallenge, showing strong antitumor immunity by immunological memory to prevent the recurrence of tumors." (PMID 36258234, 2022). "IL-6 is produced by a variety of cells including T cells, B cells, macrophages, and tumor cells." (PMID 36497467, 2022). "How is the tumour-promoting effect of IL-6 counteracted during the acute inflammatory response?" (PMID 36385095, 2022). "Likewise, interleukin 6 (IL-6), as an inflammatory mediator, has a complex role in tumor regulation with attributed pro- and anti-neoplastic properties." (PMID 36443849, 2022). "In addition, TNF-α and IL-6 have been found to promote tumor cell proliferation, invasion, metastasis and angiogenesis in cancers." (PMID 36335201, 2022). "For instance, IL-6 can promote tumor growth while IL-12 can inhibit tumor growth." (PMID 36157224, 2022).
tumor (continued). "In considering this problem, it is important to contemplate that the presence of IL-6 and other related inflammatory inhibitors of T cells in the tumour microenvironment is likely a bi-product of a range of different cell types, including tumour cells, stromal cells, and immune cells." (PMID 35359426, 2022). "Many tumor-producing factors that are critical for tumor growth and immunosuppression, such as IL-6, IL-10 and VEGF, activate STAT3 to create an efficient “feedforward” mechanism to ensure increased STAT3 activity both in tumor cells and in tumor-associated immune cells." (PMID 34875483, 2022). "Moreover, G6 treatment also induced the most secretions of cytokines in the tumor, wherein the high expressions of IL‐6 and TNF‐α in the tumor benefited CAR‐T immunotherapy against solid tumors through expanding CTLs and CAR‐T cells." (PMID 36156442, 2022). "Furthermore, the effects of tumor-derived IL-6 on the tumor and peripheral immune landscapes were explored." (PMID 36142210, 2022). "It was also shown that CXCL8/IL8 and IL6 induced the resistance of tumor cells to chemotherapy." (PMID 36354566, 2022). "This study indicated that the tumor‐derived IL‐6 promoted tumor growth of PC cells." (PMID 35578571, 2022). "Furthermore, IL-6 downstream effects also modulate the activity of neutrophils, natural killer cells, or T cells, resulting in a decreased immune response to the neoplasm, despite the apparent trafficking of these immune cells to the lesion." (PMID 36429126, 2022). "Finally, it has been discussed that increased inflammation and IL-6 secretion in adipocytes, plus a hypoxic tumor microenvironment, creates an ideal opportunity for adipocyte-derived IL6 to promote angiogenesis." (PMID 35294447, 2022). "Targeting IL-6 seems to be an attractive approach to enhance tumor response to immunotherapy." (PMID 35743911, 2022). "We further examined whether IL-6 inhibition could attenuate the effects of S. mutans on tumor aggressiveness." (PMID 36186905, 2022). "CD14CTX had increased expression of several tumor-associated macrophage (TAM)- and/or myeloid-derived suppressor cell (MDSC)-related cytokines, including IL6, TGFB1, and CXCL8." (PMID 36130508, 2022). "Targeting periostin- and IL-6- mediated tumor-stroma interaction may be an attractive therapeutic strategy for human colorectal tumors." (PMID 36077762, 2022). "After activating the myeloid differentiation factor 88 (MyD88), the invading commensal bacteria and their products interact with TLRs on tumor-infiltrating myeloid cells, leading to the production of inflammatory cytokines such as IL-23 activating the production of IL-6, IL-22, and IL-17A." (PMID 35565269, 2022). "High levels of IL-6 are also observed in case of many neoplasms." (PMID 35326644, 2022). "They, in turn, begin secreting their own inflammatory cytokines such as IL-6 and tumor necrosis factor (TNF), producing caustic reactive oxygen species (ROSs) that seep into the tumor and induce apoptosis, and intensifying their phagocytic engulfment of diseased or damaged cells." (PMID 36123677, 2022). "IL-6 signals tumor proliferation, angiogenesis, stromal cell activation and immunomodulation of the microenvironment and might induce drug resistance." (PMID 35365723, 2022). "Similarly, in murine PDAC models, IL-6 depletion specifically in αSMA+ CAFs synergizes with anti-PD-1 immunotherapy to significantly improve the survival of tumor-bearing mice." (PMID 36338519, 2022). "When NSCLC occurs, tumor-derived IL-6 stimulates PD-L1(+) myeloid cells." (PMID 35251014, 2022). "Key features of cancer-related inflammation are infiltration of white blood cells, tumor-associated macrophages (TAM), cytokines, such as IL-1, IL-6, and TNF-α, some chemokines, cell cycle acceleration, cell proliferation, evasion from apoptosis, and stimulation of tumor angiogenesis." (PMID 35163356, 2022). "IL-11 and IL-6 are tumor-promoting cytokines that function by various mechanisms." (PMID 35205776, 2022).
tumor (continued). "IL-6 is a typical proinflammatory cytokine that promotes tumor growth." (PMID 36157224, 2022). "MC-mediated anti-tumor activities relate to their ability to produce IL-1, IL-6, TNFα that induce apoptosis in tumor cells, together with chondroitin sulfate, that could exert a decoy activity by inhibiting metastases." (PMID 36338516, 2022). "Subjects of the Control and T2DM groups had similar interleukin-6 levels; and interleukin-6 was significantly higher in both tumor groups, compared to all of those observed in control groups (p < 0.0001 CRC vs Control and T2DM, p = 0.0011 CRC + T2DM vs Control, and p = 0.0069 CRC + T2DM vs T2DM)." (PMID 35071777, 2022). "Through the analysis of an epithelial-like layer of polarized Caco-2 cells that was co-cultured in the presence of CAFs and M1-type macrophages, we identified that IL-6 is the main pro-inflammatory factor responsible for inducing the overexpression of tumour-related RAC1B." (PMID 35326545, 2022). "In our study, we suggest that the interaction between the AnxA1 and IL-6 signaling pathways could be involved in the establishment of a tumor-promoting microenvironment." (PMID 35626741, 2022). "Numerous studies show that, within the tumor microenvironment, STAT3 signaling induces pro-carcinogenic cytokines (such as IL-6, IL-10, and IL-23) and inhibits anti-carcinogenic cytokines (e.g., IL-12), thereby promoting tumor immune evasion and cancer progression." (PMID 36557902, 2022). "Furthermore, stellate cells are also involved in the production/secretion of IL-6, thus the tumor microenvironment is rich in IL-6." (PMID 35626089, 2022). "In this scenario, the pro-survival activity on immune cells and the release of the immunosuppressive IL-6 in tumor microenvironment once recruited to the tumor site, could exacerbate tumor progression and likely explain therapy resistance." (PMID 36010601, 2022). "Additionally, IL-6 affects monocyte-dendritic progenitors to differentiate into metastasis-promoting cells, thereby promoting tumor aggressiveness." (PMID 35965580, 2022). "In mechanism, obese adipose tissue is regarded as chronically inflammation tissues, through expressing inflammatory cytokines such as IL-1beta, IL-6, IL-10, and TNF-alpha, cancer-associated obese adipocyte recruits macrophages, neutrophils and other immune cells into tumour microenvironment." (PMID 35296087, 2022). "Therefore, it is crucial to decipher the role of IL-6 signaling in the interplay between tumor cells and the tumor-microenvironment for the development of novel treatment modalities." (PMID 35267462, 2022). "In the clinic, tumor cells of N‐inv could be promoted by IL‐6 from both tumor cells and Schwann cells." (PMID 35578571, 2022). "In addition, G-CSF, IL-6, VEGF, and IL1-β are among the cytokines produced by tumor and stromal cells that cause neutrophilia and make these neutrophils more suppressive." (PMID 36419156, 2022). "A previous study hypothesized that IL-6 was produced not only by tumor cells to induce HNC proliferation but also by host cells (e.g., endothelial cells, stromal cells, immune cells) as a response to tumor growth." (PMID 36290836, 2022). "● Higher IL-6 levels in tumor and serum mediate muscle wasting and cancer progression." (PMID 36465353, 2022). "It has been shown that abnormally high LIF expression in the tumor microenvironment can promote macrophage aggregation, which could secrete IL6 and IL-1α to induce muscle atrophy and cachexia." (PMID 35740622, 2022). "Sunitinib decreased tumor growth and cell motility along with increased E-cadherin expression and secretion of the proangiogenic cytokines IL6 and IL8, which activated senescence in ccRCC cells and led to VE-cadherin phosphorylation, enhancing tumor angiogenesis." (PMID 36138026, 2022).